CASP4 (caspase 4)
Diseases named in the same sentence as CASP4 in open-access papers (continued):
Sharing a sentence is not in itself a finding about the gene and the disease.
tumor (continued). "Immunohistochemical staining demonstrated an increase in necrotic areas and positive staining for C-PARP, Caspase-4, p-eif2α and ERO1 in CYT997-treated tumor tissues." (PMID 30704503, 2019). "Epithelial caspase-4 expression is selectively elevated in CRC tumor tissue compared to adjacent normal tissue, where it is not expressed." (PMID 39866724, 2025). "Intestinal epithelial cells in areas of normal or inflamed tissue from CRC patients lacked caspase-4 expression, while high caspase-4 levels were detected in the epithelial cells of tumor tissue." (PMID 39866724, 2025). "This study shows that caspase-4 expression occurs selectively in the intestinal epithelial cells of dysplastic and tumor tissue, and in some, but not all, polyps." (PMID 39866724, 2025). "Regarding mechanism, lipopolysaccharide (LPS), tumor antigens, and Gram-negative bacteria are recognized by CASP4." (PMID 35000541, 2022). "Furthermore, AIM2, CASP4, GSDMB, NOD2, and RBCK1 were also found to be highly expressed in ccRCC cell lines and tumor tissues, and GASP4 and GSDMB promote ccRCC cells’ proliferation, migration, and invasion." (PMID 36248876, 2022). "The expression of caspase-4 and GSDME was significantly inhibited in the tumor tissues." (PMID 34659633, 2021). "Up-regulation of CASP4 and S100A11 may contribute to the inflammatory status in the tumor immune microenvironment for the proliferation, differentiation and survival of tumor cells." (PMID 35118063, 2021). "Additionally, the immunohistochemistry assay identified the upregulation of caspase-4, GSDMD, and phospho-RIPK3 expression in xenograft tumor tissues following NO.0449-0145 treatment." (PMID 34006852, 2021). "In addition, tissue validation results also showed that CASP4, CASP5, PRKACA, and NOD1 were differentially expressed between tumor and normal tissues from COAD patients." (PMID 34938319, 2021). "A total of 24 pyroptosis-related genes shown significantly different expression between normal and tumor tissues in COAD and seven genes (CASP4, CASP5, CASP9, IL6, NOD1, PJVK, and PRKACA) screened by univariate and LASSO cox regression analysis were used to construct the risk model." (PMID 34938319, 2021). "To note, both palmitic acid and malonic acid contents were higher in tumor-positive than tumor-negative caspase-4 tissues." (PMID 33014287, 2020). "Finally, we analyzed the proportion of tumor-infiltrating immune cells (TICs) using the CIBERSORT computational method and assessed CASP4 methylation and its relationship with drug sensitivity." (PMID 33584797, 2020). "In this latter case, a significant reduction of the arachidonic acid was observed in both tumor-positive and negative caspase-4 tissues, implying the involvement of leukotrienes, lipoxins and prostaglandins in the tumor tissue." (PMID 33014287, 2020). "Interestingly, patients with high levels of tumor-associated caspase-4 but who were c-MyC negative (c-MyC−) still had lower survival rate (median survival = 2.036 years) (blue line), although it was higher than patients positive for both Caspase-4 and c-MyC (black line)." (PMID 33187551, 2020). "In this study we found that NSCLC tissues had a positive histological score of caspase-4 which was higher in the tumor masses than in non-cancerous tissues." (PMID 33187551, 2020). "Tumor-positive caspase-4 tissues had significantly higher levels of palmitic acid than both healthy (non-cancerous) and tumor-negative caspase-4 tissues." (PMID 33014287, 2020). "Instead, a significant reduction of stearic acid, maleic acid and malic acid was observed in both tumor-positive and negative caspase-4 tissues compared to healthy, non-cancerous tissues." (PMID 33014287, 2020). "We found that caspase-4 positive NSCLC patients had a differential lipidomic signature in that both the palmitic and the malonic acid were higher present in the tumor mass of caspase-4 positive rather than negative NSCLC patients." (PMID 33014287, 2020).
tumor (continued). "We showed that caspase-4 was highly present in the tumor mass compared to non-cancerous human tissues." (PMID 33187551, 2020). "Indeed, the neutralization of IL-1α in NMU-treated mice significantly reduced the levels of tumor areas than control group and, very importantly, NSCLC patients who presented high levels of IL-1α and caspase-4 had lower median survival rate." (PMID 33187551, 2020). "Instead, we found that succinate dehydrogenase (SDHA) was higher expressed in the tumor mass of caspase-4 positive NSCLC patients compared to the non-cancerous tissues." (PMID 33014287, 2020). "Here, we analyzed the metabolomic profile of both plasma and tumor tissues of NSCLC patients stratified as caspase-4 positive or negative." (PMID 33014287, 2020). "It had been reported that many tumor cell lines and primary clinical samples express permanently elevated levels of GRP78, which might promote metastasis, inhibit caspase-4 and pro-apoptotic pathways, support chemoresistance and thereby worsen the prognosis." (PMID 30297634, 2018). "We further compared the relative expression of these molecules in 14 cancer types containing paired tumor and normal samples and found that approximately half of the autophagy regulators showed elevated expression in different cancers, including BIRC5, RIPK2, MET, ITGA6, BCL2L1, CASP4, etc.." (PMID 36261830, 2022). "In addition, normal spleen Treg, normal tissue Treg, non-tumor diseased spleen Treg, non-tumor diseased tissue Treg, tumor spleen Treg and tumor Treg had 8, 10, 2, 9, 11, and 9 specific upregulated caspase-4 secretomic pathways, respectively." (PMID 34084175, 2021). "We hypothesized that caspase-1- dependent secretomic transcripts and caspase-4-dependent secretomic transcripts are modulated in Treg from normal tissues, non-malignant disease Treg, and Treg from tumor spleens and tumors." (PMID 34084175, 2021). "Similarly, we found that malonic acid content was significantly higher in tumor-positive caspase-4 tissues than in healthy, non-cancerous, and tumor-negative caspase-4 tissues." (PMID 33014287, 2020). "Similarly, transcriptional levels of CASP4 mRNA were higher in the tumor mass than in healthy (non-cancerous) tissues of NSCLC patients." (PMID 33187551, 2020). "Moreover, no statistical differences were observed among the tissues (healthy, non-cancerous, vs tumor-caspase-4 + and caspase-4 -) about the contents of succinic acid, oleic acid, myristic acid, linoleic acid and arachidic acid, but not of arachidonic acid." (PMID 33014287, 2020). "Herein, caspase-4 could be identified as a novel oncoprotein since 79.3 and 88.2% of adenocarcinoma and squamous NSCLC patients, respectively, stained positive for the protein which pro-tumor activity was reflected in a concerted cooperation with mutated K-Ras and cMyC." (PMID 33187551, 2020). "Moreover, 33.78% of tissue-caspase-4 positive NSCLC patients (25 out of 74) were LDH negative (red bar on the right), implying that in the tumor mass, differently than what observed in the blood, a differential metabolic pattern can exist." (PMID 33014287, 2020). "Moreover, tumor lysates obtained from LoVo and SW480 xenograft mice treated with SSa for 10 days also showed cleavage of caspase-4 (data not shown)." (PMID 29245990, 2017).
infection (68 papers, 2010 to 2026). The state of being infected such as from the introduction of a foreign agent such as serum, vaccine, antigenic substance or organism. "The protein expression of three proteins (IL-8, CXCL9, and CXCL10) were significantly increased in caspase-4-deficient cells compared to Cas9 cells following HK1651 infection." (PMID 40137780, 2025). "Paralleling the impact of caspase-4 and caspase-5 on IL-1β release, during infection with M. kansasii, their absence was associated with a twofold reduction in cell death to baseline." (PMID 40272180, 2025). "Caspase-1- and caspase-4-deficient cells showed significantly altered cytokine and chemokine profiles after infection with A. actinomycetemcomitans, showing reduced IL-17C and IL-18 release." (PMID 40137780, 2025). "The protein expression of two proteins (IL-17C and IL-18) was significantly decreased and the protein expression of two proteins (TGF-α and LIF) was significantly increased in caspase-4-deficient cells compared to Cas9 cells following HK1651 infection." (PMID 40137780, 2025). "During infection of exogenous pathogenic microorganism, many types of murine Gbps and human Gbp2 and Gbp5 can trigger the host cells’ pyroptosis by activating inflammasome complex containing caspase-1 or caspase-4." (PMID 32731337, 2020). "CASP4–/– cells with intact NAIP–NLRC4 responses showed enhanced cell death upon infection with ΔospF Shigella, and complementation with plasmid-encoded OspF fully reversed the enhanced death seen with ∆ospF." (PMID 41533441, 2026). "We found that the caspase-1- and caspase-4-deficient cells exhibited significantly increased proliferation compared to Cas9 cells during unstimulated conditions and during HK1655 infection." (PMID 40137780, 2025). "In this study, we show that caspase-1 is required to restrict intracellular Salmonella replication early during infection in human macrophages, and that caspase-4 enables the restriction of Salmonella later during infection." (PMID 40162563, 2025). "We continued to investigate the role of caspase-1 and caspase-4 in the release of chemokines from gingival epithelial cells after infection with HK1651 for 24 h." (PMID 40137780, 2025). "WT and CASP4-/- cells also released similar levels of the inflammasome-independent cytokine TNF-α upon infection with WT Salmonella at 24 hpi." (PMID 40162563, 2025). "Casp4, a gene related to the formation of NETs, was upregulated in Il1bhi Neu near the infection foci." (PMID 39985260, 2025). "Caspase-4 contributes to the control of Salmonella replication within human macrophages later during infection." (PMID 40162563, 2025). "Whereas caspase-1 is the primary caspase that mediates inflammasome responses and control of Salmonella burdens in human macrophages, our data indicate that caspase-4 also plays a role at a later stage of infection." (PMID 40162563, 2025). "Altogether, these results suggest that caspase-4 plays a larger role in controlling Salmonella burdens later during infection." (PMID 40162563, 2025). "Next, we continued to investigate the role of caspase-1 and caspase-4 in the release of additional inflammatory mediators from gingival epithelial cells after infection with HK1651 for 24 h." (PMID 40137780, 2025). "In contrast, caspase-4 contributed minimally early during infection and instead played a larger role in inflammasome responses and restriction of Salmonella replication at later timepoints." (PMID 40162563, 2025). "The data also indicated that caspase-4 and caspase-5 mRNA levels were greatly elevated after 4h post-infection." (PMID 37180156, 2023). "The NLRP3 inflammasome can be activated by a variety of stimuli during infection, including potassium efflux downstream of caspase-4-dependent GSDMD activation and pore formation (5, –, 9)." (PMID 37615436, 2023).
infection (continued). "CASP4−/− THP-1 macrophages also had reduced levels of inflammasome activation during Δ6 Yptb infection, suggesting that like in human IECs, caspase-4 contributes to Δ6 Yptb-induced inflammasome activation in human macrophages." (PMID 37615436, 2023). "Although pyroptosis can be induced by a non-canonical pathway that is activated by the direct interaction between caspase-4/5/11 and cytosolic lipopolysaccharides, we focused on investigating the canonical pathway during infection." (PMID 37457695, 2023). "WT THP-1s treated with either CASP4 or CASP5 siRNAs exhibited significantly decreased IL-1β secretion following WT Stm infection relative to WT THP-1s treated with control siRNA, in agreement with our previous observations in primary human macrophages." (PMID 35073381, 2022). "MERS-CoV infection of HMECs resulted in upregulation of 1.55, 3.84, 4.5, and 4.99% of caspase 4 SGs at 12-, 24-, 36-, and 48-h post-infection, respectively." (PMID 35320939, 2022). "The infection of Salmonella typhimurium can also lead to the activation of Caspase 4, and Caspase 4 can limit the replication of S. typhimurium in the cells." (PMID 35722038, 2022). "Mouse caspase-11 and its human ortholog caspase-4/5 are identified as a sensor of intracellular pathogen infection." (PMID 35473933, 2022). "We tested the contribution of Caspase-4 in PMN-mediated epithelial cell shedding during STM infection by treating PMN-HIOs with a Caspase-4 inhibitor (z-LEVD-FMK)." (PMID 36191054, 2022). "Consistent with previous reports studying STM-infection in human epithelial models, we did measure a significant increase in Caspase-4 and Caspase-5 transcript levels." (PMID 36191054, 2022). "We found 26 proteins that were significantly altered by the CFT073 infection in caspase-1, caspase-4 or NLRP3-knockdown cells compared to CFT073 stimulated Cas9 control cells or compared to their own unstimulated controls." (PMID 35132157, 2022). "In contrast, 5448 infection increased caspase-4 expression at 30 (p<0.01), 60 (p<0.001) and 180 min compared to uninfected neutrophils (p<0.0001)." (PMID 33585270, 2020). "Concurrently, coordinated induction of the pro-inflammatory signaling via TLR4 and/or caspase-4/11 pathways is believed to mount an advantageous immune activation aimed at protection from infection and management of chronic inflammation." (PMID 33329561, 2020). "Our findings establish a crosstalk between caspase-4 and caspase-1 during natural infection by virulent EPEC." (PMID 31018119, 2019). "Consistent with a temporally early role of caspase-4 in EPEC-induced pyroptosis, immunoblots showed caspase-4 activation in cell lysates within 1 h of infection, whereas cleaved caspase-1 and GSDMD proteins were detected at 3 and 5 h post-infection." (PMID 31018119, 2019). "In our study, too, atypical NLRP3 activation by natural infection of MDMs by EPEC differed from caspase-4-signaling upon LPS transfection." (PMID 31018119, 2019). "Infection with E. coli resulted in increased expression of cleaved caspase-4 in WT and ASC-/- cells (P = 0.001 and P = 0.004, respectively) at 6 h." (PMID 30087667, 2018). "We observed an induction of the expression of two other inflammatory caspases, caspase-4 and 5 upon infection, which was confirmed by immunoblot analysis." (PMID 29339744, 2018). "The caspase-4-dependent response to F. novicida LPS is a physiological response as it fully controls IL-1β release and cell death upon infection of hMDMs." (PMID 29339744, 2018). "NleF is a potent inhibitor of mammalian caspase-4/11 and thus prevents IL-18 secretion in vitro, and it blocks caspase-11-IL-18-mediated neutrophil influx during infection." (PMID 28593173, 2017). "In our study, expression of TLR4, TLR5, NLRC4, caspase-4, and matured IL-18 and IL-1β cytokines was induced in hCFs after infection with P. aeruginosa wild-type strains." (PMID 28469996, 2017).
infection (continued). "The subfamilies of inflammatory mediator (Casp1, Casp4) were up-regulated in response to infection with both B. pseudomallei WT and BM16." (PMID 27634329, 2016). "Taken together, the current literature suggests that human orthologs caspase-4 and -5 function similarly to murine caspase-11 in the activation of the noncanonical inflammasome and induction of pyroptosis in response to infection and LPS detection." (PMID 26426007, 2015). "We observed substantial levels of GSDMD-dependent cell death in mT3Sf-infected CASP4–/– cells (mediated by NLRC4) and in NLRC4–/– cells (mediated by CASP4), confirming that mT3Sf::empty infection induces pyroptosis via activation of both of these two main cell death pathways." (PMID 41533441, 2026). "By influencing these pathways, caspase-4 may contribute to sustained inflammatory responses, further amplifying immune activation in response to infection." (PMID 40137780, 2025). "At 4 h of infection with M. kansasii and 24 h of infection with M. tuberculosis, the absence of caspase-4 and caspase-5 was associated with a complete absence of IL-1β release." (PMID 40272180, 2025). "While our findings offer valuable insights into the role of caspase-4 activation in P. gingivalis-LPS infection, it is important to acknowledge potential limitations and the possibility of compensatory mechanisms that may influence the observed outcomes." (PMID 40497980, 2025). "Notably, consistent with both Δ6 and ΔyopEHK Yptb infection, we found that caspase-4 was absolutely required for inflammasome activation induced by ΔyopEH Yptb." (PMID 37615436, 2023). "Caspase-4 contributed to cell lysis even when the intracellular bacteria lacked the entire T33S and were consequently unable to escape vacuoles, representing a naturally occurring subpopulation during wild-type infection." (PMID 37589460, 2023). "Moreover, the caspase-4/pro-caspase-4 ratio was increased also in HeLa cells after infection with either B1940 or B1940ΩhrpA compared to non- infected cells (~ 50% ± 0.20)." (PMID 35765029, 2022). "Similarly, infection with S. flexneri was responsible for caspase-4 driven inflammatory cell death in HaCaT keratinocytes and human colon adenocarcinoma HT29 cell line." (PMID 33329561, 2020). "5448AP infection however, only increased caspase-4 expression at 180 min (p<0.01)." (PMID 33585270, 2020). "Overall, our results converge to a novel pathway, which relies on influx of Ca2+ through the plasma membrane during infection with an extracellular pathogen, in a Tir-dependent manner, leading to LPS internalisation followed by caspase-4-mediated GSDMD cleavage." (PMID 33378358, 2020). "The Shigella effector OspC3 antagonizes the human LPS sensor CASP4, and IEC-expressed CASP4 provides protection against other human bacterial pathogens, underscoring the importance of the LPS-sensing pathway during human infection." (PMID 33074100, 2020). "Because our data demonstrated that hemolysin increased caspase-4 activation in intestinal epithelial cells, it is reasonable to speculate that hemolysin may promote cytosolic release of bacterial LPS during infection." (PMID 30138458, 2018). "Caspase-4 pro-enzyme and pro-IL-18 protein expression was found to be constitutive, whereas pro-IL-1β was induced by P. aeruginosa wild-type infection, reduced by infection with the ΔpopB mutant and very weakly induced by infection with the PA14 ΔflgK mutant." (PMID 28469996, 2017). "In addition, we discuss the potential implications of a danger signal, eATP, and ROS generation as novel inducers of human caspase-4 and -5 pathways during infection." (PMID 26426007, 2015). "Hence, exploration into human caspase-4 and -5 function and regulatory mechanisms will provide critically novel insight into the regulation of human innate immune responses to pathogen infection at epi-mucosal sites and in immune cells." (PMID 26426007, 2015).